NF2 (NF2, moesin-ezrin-radixin like (MERLIN) tumor suppressor)
Diseases named in the same sentence as NF2 in open-access papers (continued):
Sharing a sentence is not in itself a finding about the gene and the disease.
meningioma (continued). "Meningioma-associated NF2 mutations commonly result in a truncated, non-functional protein, which may lead to abnormal cell growth and motility through destabilization of adherens junctions." (PMID 25965831, 2015). "Although not all cases have a meningeal component and malignancy characteristics are typically absent, the association between meningioma in rare cases and molecular aberrations regarding the NF2 gene in both lesions suggests that MA may be correlated with meningioma." (PMID 25886050, 2015). "Besides, NF2 gene expression was low in 13 of the 21 meningiomas analyzed." (PMID 25247996, 2014). "However, loss of chromosome 22 and/or del(22q) are only found in a fraction of all meningiomas suggesting that molecular and chromosomal changes other than those targeting the NF2 gene may also be involved in the development of meningiomas." (PMID 24171707, 2013). "However, careful analysis of the studies reported so far reveals that the association between chromosome 22 status and the presence of NF2 mutations has not been investigated in detail in sporadic meningiomas." (PMID 24171707, 2013). "In fact, it has been shown that meningiomas may be grouped into tumors with and without mutations in the NF2 gene." (PMID 17222329, 2007). "As the first NF2-SWN-related meningioma cell line, AG-NF2-Men is a unique reagent for investigating meningioma biology and therapeutics." (PMID 41417846, 2026). "Clinical studies revealed that YAP fusion, particularly with MAML2, occurs in a subset of pediatric NF2-wildtype meningiomas, and the YAP1-MAML2 fusion is similar to NF2 mutant meningioma." (PMID 39894505, 2025). "Exploratory biomarkers include hippo/YAP activity signatures, which are enriched in NF2- and YAP1-driven meningiomas." (PMID 41487565, 2025). "Data from 20 studies (2011–2023), including 1010 pediatric meningioma cases, were analyzed to assess PFS and OS stratified by WHO grade, NF1/NF2 status, extent of resection (EOR), and adjuvant radiotherapy." (PMID 39779595, 2025). "NF2-SWN usually presents with bilateral vestibular schwannoma, but can present with meningioma or spinal tumour or ophthalmic features before a VS diagnosis or with a unilateral VS and other tumours and rarely with a unilateral VS alone." (PMID 41160189, 2025). "Together, these data indicated similarities between NF2-SWN meningioma or VS with their sporadic counterparts, as well as similarities in cellular growth and proliferation between meningioma and VS overall when compared against their control tissues." (PMID 41437121, 2025). "Two human meningioma cell lines were used in this study, including NF2-wildtype IOMM-Lee cell and NF2-null CH157-MN cell." (PMID 39894505, 2025). "Furthermore, the findings suggest that IOMM-Lee meningioma cells may not originate directly from mutations in the NF2 gene." (PMID 39894505, 2025). "Many gene fusions are oncogenic, and gene fusions have been reported in meningiomas, particularly NF2 structural rearrangements in radiation-induced meningiomas, and YAP1 fusions in rare pediatric meningiomas." (PMID 38509407, 2024). "A meningioma is a tumor that originated from the meninges with alterations in NF2, AKT1, TRAF7, SMO, and PIK3C, and most meningiomas are benign." (PMID 38540119, 2024). "Importantly, YAP fusions seemed to arise in pediatric meningiomas without NF2 mutations." (PMID 40491864, 2024). "NF2-SWN affects approximately one in twenty-five thousand individuals worldwide, who develop multiple benign tumors, including schwannomas, meningiomas, and ependymomas throughout their life." (PMID 38945076, 2024). "Recently, the expression of Merlin/Neurofibromin2 (NF2) and the ferroptosis regulator GPX4 were positively correlated in the case of primary meningioma." (PMID 38540208, 2024).
meningioma (continued). "The importance of the PI3K-AKT-mTOR pathway in the pathobiology of meningiomas is furthermore emphasized by the fact that chr 10q, harboring the PTEN gene, an inhibitor of this pathway, is frequently lost in high-grade NF2 mutant meningiomas." (PMID 38571886, 2024). "Previous investigations have identified Wnt pathway activation across meningiomas with SSVs targeting TRAF7, KLF4, PIK3CA, POLR2A, the Hedgehog pathway, and even NF2 and SMARCB125." (PMID 39251601, 2024). "Interestingly, this meningioma subtype was significantly correlated with a lack of NF2 mutations, which suggests that novel mutations in KLF4 and TRAF7 may both be mutually exclusive to alterations in NF2111." (PMID 38879686, 2024). "Deletion of the NF2 gene was identified in two cases with multiple MMNs, one PPM, and four CNS meningiomas." (PMID 36832290, 2023). "The remaining metastasizing case (#1) had copy number losses in NF2 and PTEN and was histologically an atypical meningioma, CNS WHO grade 2." (PMID 36641486, 2023). "This analysis highlighted the unique transcriptional profiles of NF2 and TRAF7 meningiomas, indicating that tumor-specific genetic alterations lead to activation of divergent signaling pathways in these tumor cells." (PMID 36937440, 2023). "Specifically, NF2 meningiomas expressed higher levels of arachnoid CLDN11 and pial LAMA2, while TRAF7 tumors overexpressed dural MGP and dural/arachnoid CRABP2 relative to NF2 tumors." (PMID 36937440, 2023). "The meningiomas harboring YAP1-MAML2, which is the most frequent fusion subtype, exhibit activated YAP1 signaling and share similarities with NF2 (neurofibromatosis type 2 gene) mutant meningiomas." (PMID 37628996, 2023). "They identified 4 molecular subgroups of meningioma, MG1-4, and designated each subgroup based on pathway analysis of enriched genes: immunogenic (MG1), benign NF2 wild-type (MG2), hypermetabolic (MG3), and proliferative (MG4)." (PMID 35402234, 2022). "In addition, NF2 alterations combined with abnormalities in AKT1 and mTOR are associated with the overgrowth of various tissues, which could be responsible for the recurrence of meningiomas." (PMID 35712491, 2022). "Based on tumor expression, therapeutics directed toward NF2 and topoisomerase IIA would benefit the vast majority of meningioma patients." (PMID 36497370, 2022). "The combination of NF2 alteration, high Ki-67 and supratentorial location defines subgroup with the worst prognosis among WHO grade I meningiomas." (PMID 35570314, 2022). "In a recently published study, researchers evaluated the expression of Merlin/Neurofibromin2 (NF2) and the ferroptosis regulator GPX4 in patients with primary meningioma and found a positive correlation between them." (PMID 35530363, 2022). "However, the NF2 gene fusion-based biomarker for the prediction of meningioma progression or recurrence might not be reliable in clinical practice as radiation therapy could induce new NF2 mutations or structural variants in meningioma." (PMID 33807688, 2021). "A recent large genetic analysis found high rates of NF-2 and POLR2A alterations in posterior fossa region meningiomas." (PMID 34638590, 2021). "In summary, this present observation demonstrates the inhibitory effect of chrysophanol on malignant meningioma cells and its regulatory roles in the signaling transduction of OGN/mTOR and NF2 cascades." (PMID 33622177, 2021). "HBL-52 meningioma cells overexpressing OGN showed increased levels of activated mTOR and down-regulated NF2 protein at 48 h (p< 0.05)." (PMID 33622177, 2021). "Meningiomas, rare in children, make up only 3% of pediatric SNC tumors and are closely related to the diagnosis of NF2; it is estimated that 20% of NF2 patients harbor spinal meningiomas." (PMID 34574050, 2021).
meningioma (continued). "The higher risk of recurrence associated with posterior fossa location may be due to the increased prevalence of NF2 mutations in the posterior fossa, although we are unable to fully explore this as we do not routinely perform genetic testing of meningioma at our institution." (PMID 32983999, 2020). "As previously shown, aberrant promoter methylation of CpG islands via IL-1b can silence the NF2 gene, which has pivotal roles in tumorigenesis and the development of WHO grade I meningiomas." (PMID 33014773, 2020). "To evaluate the effect of this drug on schwannoma cells in comparison to meningioma cells, we compared mifepristone-treated primary human VS and HEI-193 cells to immortalized human arachnoid cells in which the NF2 gene has been excised by CRISPR40." (PMID 29615643, 2018). "This gene showed increased H3K27ac binding in atypical versus benign meningiomas (FDR=0.007, fold change log FC=4.95) with increased expression in atypical NF2 samples (gene expression FDR=0.001)." (PMID 28195122, 2017). "Although the somatic mutations sometimes overlap with those in hereditary NF2, there are no published papers documenting an increased risk of cancer in neurofibromatosis patients; individuals with hereditary NF2 do develop schwannomas, ependymomas, and meningiomas." (PMID 24393766, 2014). "The mice with both Nf2 and Cdkn2ab inactivation lead to short latency of tumor development and the ability to induce grade II/III meningioma progression." (PMID 25247996, 2014). "In addition to the inactivation of the neurofibromin gene, NF2, which is considered to be an early step in tumorigenesis, variations of other biological regulatory pathways may play a significant role in the development of meningioma." (PMID 23946817, 2013). "Anatomically, the non-skull base posterior midline (NSB-POST-M) meningiomas had the lowest Vi in both cohorts and the NF2-driven subset indicating that these tumors exhibit aggressive features even at smaller sizes." (PMID 40569492, 2025). "Given the limited information about the predictive value of Merlin IHC in detecting NF2 alterations in meningioma, this study investigated the immunostaining pattern of Merlin in a case series of CNS WHO grade I meningiomas and compared it with their genetic abnormalities." (PMID 40815185, 2025). "The identification of LZTR1 in 2014 as a cause of the related schwannomatosis condition (multiple schwannomas but a lack of meningiomas, VS and ependymoma) resulted in significant clinical overlap between NF2-SWN and LZTR1-SWN." (PMID 41160189, 2025). "In contrary, lead exposure did not significantly affect the proliferation of the NF2-null meningioma cell line CH157-MN." (PMID 39894505, 2025). "Expression patterns further demonstrated tissue specificity, exemplified by its correlation with NF2 in meningiomas and normal nervous system tissues, whereas no such relationship was evident in tumors of non-neural origin (Lei, Cai & Yan, 2024)." (PMID 41180485, 2025). "Recent multiomics analyses also suggested that groups of meningioma with multiple CNVs in addition to NF2 alterations tended to show poorer outcomes than a group of NF2‐altered meningioma without CNVs and a group of NF2‐intact meningioma." (PMID 40815185, 2025). "Our results suggested that lead exposure promoted NF2-wildtype but not NF2-null meningioma cells proliferation." (PMID 39894505, 2025). "Such factors likely vary by tumor grade, location and tumor subtype, meaning FAK dependency is not uniform across NF2-mutant meningiomas." (PMID 41487565, 2025). "What is striking is that this vulnerability remained unnoticed for years - not because it lacked scientific plausibility, but because NF2-mutant meningiomas were not prioritized." (PMID 41487565, 2025).
meningioma (continued). "A global proteomic analysis revealed unique protein expression patterns in all three genetically distinct meningioma groups AKT1E17K/TRAF7, KLF4K409Q/TRAF7, and NF2−/− when compared to normal meningeal tissue allowing further exploration of these targets for personalised therapy." (PMID 40562609, 2025). "Another likely limitation of this pilot study is that the examination of meningioma recurrence was limited to 1p-22q-NF2- tumors and did not include analysis of other meningioma subtypes, including 14q-22q- group tumors." (PMID 39726707, 2024). "Our results demonstrate that 1p-22q-NF2- meningiomas without expression of GSTM1 comprise the recurrent 1p-22q-NF2- meningiomas compared to those that express GSTM1, thereby addressing the heterogeneity in this existing molecular classification scheme." (PMID 39726707, 2024). "Alterations to YAP1 have been reported in 9 paediatric meningiomas, specifically sporadic cases lacking in NF2 alterations." (PMID 39612013, 2024). "First, we only used two representative malignant meningioma cell lines, IOMM-Lee without NF2 mutation and CH157 with NF2 mutation, to explore the regulation and roles of the CBX7/USP44/c-MYC/LDHA axis." (PMID 37791390, 2024). "RNA-Seq data from large numbers of human meningiomas when displayed in a UMAP shows significant correlation between expression patterns, and clinical and genomic data, such as tumor grade, time to recurrence, functional NF2 status." (PMID 38571886, 2024). "Meningiomas without NF2 alterations are clinically benign and typically localized to the medial skull base." (PMID 39066986, 2024). "Moreover, in MPM and meningioma, TRAF7 and NF2 also exhibit mutually exclusive relationships, which suggests that they are involved in a common signalling cascade." (PMID 38879686, 2024). "Consistent with this, high activity of NK cells was observed in meningiomas of NF2 patients and in non-recurrent cases in our study." (PMID 37752594, 2023). "Transcriptomic analysis for patients with NF2/sporadic NF2-altered WHO grade I meningiomas (n = 14 vs. 15, respectively) showed that tumours in NF2 patients still had a higher immune response and immune cell infiltration than sporadic NF2-altered meningiomas." (PMID 37752594, 2023). "It has recently been proposed that meningiomas may be classified into four molecular groups (MG): immunogenic (MG1), benign NF2-wildtype (MG2), hypermetabolic (MG3), and proliferative (MG4)." (PMID 37014425, 2023). "Univariate and multivariate analyses for Grade II/III NF2-altered meningiomas showed that high Ki–67 index and male sex were predictors of high-grade meningiomas, and the germline NF2 alteration did not represent a significant predictive factor." (PMID 37752594, 2023). "Interestingly, both NF2 and TRAF7 meningiomas possess upregulated genes of canonical members of the fibroblast growth factor (FGF) family." (PMID 36937440, 2023). "Nonetheless, as more cases of YAP1 fusion meningiomas are identified and analyzed, it becomes evident that certain subtypes, such as YAP1-FAM118B fusion, exhibit distinct biological characteristics from the NF2 mutant." (PMID 37628996, 2023). "Accordingly, contrary to previous reports, our results clearly showed that meningiomas in NF2 patients are not histologically or clinically more aggressive than sporadic NF2-altered meningiomas, which is in line with the latest two reports." (PMID 37752594, 2023). "Later, genomics studies identified numerous meningioma genetic alterations, many of which were not in the NF2 gene." (PMID 38001599, 2023). "Mutations in Krüppel-like factor 4 (KLF4), a transcription factor in oncogenic activation, have been detected in about 50% of NF2-nonmutated meningiomas." (PMID 37760490, 2023). "In sum, our results shed light on Merlin posttranslational modifications that regulate meningioma Wnt signaling and tumor growth in tumors without NF2/Merlin inactivation." (PMID 36993679, 2023).
meningioma (continued). "Although recent molecular analyses revealed that sporadic meningiomas have various genetic, epigenetic, and transcriptomic profiles, meningioma in patients with neurofibromatosis type 2 (NF2) have not been fully elucidated." (PMID 37752594, 2023). "Rescue of MerlinS13D but not MerlinS13A sequestered β-catenin at the plasma membrane in meningioma cells, and MerlinS13A but not MerlinS13D rescued Wnt signaling in meningioma cells lacking NF2." (PMID 36993679, 2023). "According to the latest two reports, meningiomas in NF2 patients are not histologically or clinically more aggressive than sporadic NF2-altered meningiomas." (PMID 37752594, 2023). "When integrating all clinical factors (excluding treatment-related factors) in a linear regression model we found that S100-strong meningiomas were independently associated with female gender, lower WHO grade, NF2 and non-skull base location." (PMID 35838837, 2023). "Broadly, NF2 SSVs with or without chromosome 22q deletion affecting the NF2 locus are by far the most common genomic alteration, with biallelic NF2 inactivation affecting 40–60% of meningiomas." (PMID 36315366, 2022). "A gene involved in the growth of NF2-negative meningiomas is TRAF7, an E3 ubiquitin ligase that interacts with MEKK3/MAP3K3 (mitogen-activated protein kinase kinase 3) and regulates apoptosis." (PMID 35565385, 2022). "Whereas, the difference in number of multiple meningiomas between NF2 mutant and wild-type groups had no statistical significance." (PMID 36267986, 2022). "As expected, NF2 alteration was more often present in WHO grade 2 and 3 tumors than in grade 1 (respectively 18/27 vs. 11/36, p = 0.01) and in the skull convexity meningioma in comparison to the skull base ones (18/30 vs. 4/21 p = 0.0037)." (PMID 36139608, 2022). "Whereas the prognosis of meningiomas differs depending on their epigenomic/transcriptomic profile, the effect of NF2 alteration on the prognosis of benign meningiomas is not fully elucidated." (PMID 35570314, 2022). "We have demonstrated that targeting the Pi3K-AKT-mTOR pathway is relevant in all meningiomas; regardless of any mutations of Pi3K or AKT components but also NF2 status." (PMID 36139608, 2022). "In the 40% of meningiomas that do not have NF2 inactivation, alternative explanations are sought to explain meningioma tumorigenesis." (PMID 36686824, 2022). "Multivariate analysis showed that NF2 meningioma per se was not proven to be a predictor of prognosis." (PMID 35570314, 2022). "Our study was performed in vitro on the human meningioma cell lines and on a large series of primary cultures providing from 63 freshly operated meningiomas including 35 WHO grade 1, 23 grade 2, and five grade 3, half of which presented a NF2 genomic alteration." (PMID 36139608, 2022). "Consistent with intracranial meningiomas, the histologic subtype of NF2-mutant meningiomas was variable (7 meningothelial, 16 psammomatous, 4 transitional, 5 fibrous), while all but 1 AKT1-mutant meningioma showed a meningothelial histology (93.3%, p = 0.0001)." (PMID 35943573, 2022). "Corroborating their results, NF2 meningioma per se was not a significant predictor by multivariate analysis for PFS in WHO grade I meningiomas in the current study." (PMID 35570314, 2022). "YAP1-MAML2 fusions have been reported in NF2-wild type meningioma and other cancers, but not schwannomas." (PMID 35986430, 2022). "Epidemiological molecular data are lacking; based on the largest genomic study to date, NF2 remains the most commonly affected gene in meningiomas." (PMID 33262459, 2021). "Multiple meningiomas with and without NF2 alterations are present in 1% and 4% of patients, respectively." (PMID 33801089, 2021).